STAT3 (signal transducer and activator of transcription 3)
Diseases named in the same sentence as STAT3 in open-access papers (continued):
Sharing a sentence is not in itself a finding about the gene and the disease.
cancer (continued). "Since both FAS and IL6 were closely associated with cancer pathogenesis and STAT3 activation, we investigated IL6 mRNA and protein levels after FAS knockdown." (PMID 32963220, 2020). "Although the development and progression of cancer cachexia due to overactivation of STAT3 is unclear, increased activation of STAT3 has been associated with loss of muscle mass in several mice models." (PMID 32230855, 2020). "Analysis of transcriptomic and drug susceptibility data from hundreds of cancer lines reveals a STAT3-dependent gene-set predictive of susceptibility of cancers to synthetic lethal PARP inhibition." (PMID 33002095, 2020). "We divided TFs into three categories: the first one is represented by TFs whose splice variants affect the cancer cell phenotype by regulating different classes of genes (NF-YA, STAT3, TCF4 and WT1)." (PMID 32244895, 2020). "We suggest that the miR-125b-5p/STAT3 pathway can serve as a potential target for the treatment of cancers associated with dysregulated mTORC1." (PMID 31949495, 2020). "The enhanced secretion of leptin has been linked to cancer cell growth and migration by inducing the activation of STAT3, MAPK, JAK/STAT signaling pathways." (PMID 32596159, 2020). "NF-κB and signal transducer and activator of transcription 3 (STAT3) association triggers inflammation and cancer." (PMID 32781533, 2020). "So, we evaluated the association between STAT3 expression and the response to 545 drugs in 823 cancer cell lines by CCLE and CTRP." (PMID 32486001, 2020). "In this review, we mainly focused on the role of STAT3 in response to radiotherapy, and the underlying mechanisms including but not limited to apoptosis, aggressive behaviors, DNA damage repair, cancer stem cells were discussed." (PMID 32733808, 2020). "It has an essential role in activating JAK2 (janus kinase 2), which causes a persistent STAT3 (signal transducer and activator of transcription 3) activation in cancers." (PMID 32887262, 2020). "Several studies have demonstrated that NF-κB bound to STAT3 induces hTERT expression via binding to the hTERT promoter, which is significantly associated with aggressiveness and poor survival of patients with cancer." (PMID 31952344, 2020). "Aberrantly expressed STAT3 is known to elevate the transcriptional gene expression of proteins implicated in various hallmarks of cancer development, including uncontrolled cell growth and survival." (PMID 31936675, 2020). "A wealthy body of evidence has shown that the IL-6/JAK/STAT3 signaling pathway is aberrantly activated in many types of cancer and associated with a poor prognosis." (PMID 32127934, 2020). "As a critical oncogene, STAT3, has been proven to be associated with malignant tumor progression, through processes such as proliferation, migration, and invasion." (PMID 32471980, 2020). "Signal transducer and activator of transcription (STAT) proteins, and in particular STAT3, have been established as heavily implicated in cancer." (PMID 32872372, 2020). "The variant FGFR4 p.Gly388Arg has been shown to penetrate the STAT3 molecule into the cell membrane and impact cell surface molecules, thereby accelerating the progression of cancer and becoming an important risk factor for the progression of the disease." (PMID 33456465, 2020). "In many types of cancer patients, excessive activity of STAT3 is associated with poor survival outcomes." (PMID 33003453, 2020). "Strong STAT3 expression in cancer cells results from the loss of inhibitory signals and the predominance of factors causing its continuous activation." (PMID 33158194, 2020).
cancer (continued). "The up-regulation of S1PR1 activity has a central role in sustaining persistent activation of transcription factors NF-κB and STAT3 in a feed-forward amplification loop that promotes chronic inflammation and colitis-associated cancer." (PMID 32456134, 2020). "As we all known that transcription factor signal transducer and activator of transcription 3 (STAT3) is closely associated with apoptosis in cancer." (PMID 32489321, 2020). "Several studies have shown that a greater feedback activation of signal transduction activator of transcription 3 (STAT3) is at the basis of the resistance mechanisms of oncogene-addicted cancers and their associated metabolic reprogramming." (PMID 32825551, 2020). "In contrast, STAT3 becomes hyperactivated in the majority of human cancers and is generally associated with poor clinical prognosis." (PMID 32972405, 2020). "Further, a number of reports have also revealed that the cytokine-induced activation of STAT3 is associated with the evasion of apoptosis, among other cancer hallmarks." (PMID 31936675, 2020). "Intriguingly, Stat3 blunted C/EBPdelta action in C2C12 myotubes for both MuRF1 and MAFbx, whereas both Stat3 and C/EBPdelta seemed necessary for the development of cancer-linked muscle atrophy." (PMID 32933049, 2020). "Elevated and increased nuclear level of STAT3 and p-STAT3 have been reported to be associated with invasiveness of the disease and advanced stages of the cancer." (PMID 32046095, 2020). "Studies have also shown that abnormal activation of Stat3 was associated with poor prognosis in cancer patients." (PMID 32258099, 2020). "It is confirming that the antiesophageal cancer effect of CT was associated with the inhibition of IL-6–mediated activation of JAK2/STAT3 signaling pathway." (PMID 32265690, 2020). "Both are induced by the TIE2 mutant variant R849W; however, STAT3 is implicated in the pathogenesis of many cancer types." (PMID 33634164, 2020). "IL-17 is implicated in early intestinal inflammation and promotes cancer cell survival and proliferation and consequently triggers IL-6 production that activate STAT3 pathway." (PMID 32863742, 2020). "Many downstream genes of STAT3 have been identified in human cancers, including genes associated with cell cycle (cyclin D1 and cMyc), apoptosis (Bcl2-xL and Mcl-1) and metastasis (MMP1 and MMP2)." (PMID 32161621, 2020). "The oncogenic transcription factor Signal transducer and activator of transcription 3 (Stat3) is associated with cancer progression, metastasis, chemoresistance, stem cell self-renewal and maintenance, autophagy, and immune evasion." (PMID 32630026, 2020). "Several infectious agents depend on STAT3 activation to cause inflammation-induced cancer; for example, H. pylori-induced gastric cancer." (PMID 32824207, 2020). "In fact, STAT3 interacts with NF-κB in context-dependent manners to promote several cancer hallmark characteristics including: the inhibition of cell death, increased proliferation, survival, and inflammation." (PMID 32414156, 2020). "The therapy 5-FU and resveratrol combination treatments cause anti-cancer activities by inhibiting STAT3 and Akt signaling pathways, thereby increasing CRC cell apoptosis." (PMID 32731413, 2020). "STAT3 signal is frequently activated during cancer development and associated with different characteristics of cancer." (PMID 32661236, 2020). "Altogether, the findings of the current study suggest that SNG has anticancer potential against PTC cells as well its derived cancer stem-like cells, most likely via inactivation of STAT3 and its associated signaling molecules." (PMID 32182833, 2020).
cancer (continued). "A recent study has shown that neural adhesion molecule L1 promotes EC proliferation and migration through the IL-6/JAK/STAT axis, and IL-6-mediated STAT3 phosphorylation is associated with EndMT and promotes cancer growth." (PMID 32296578, 2020). "In patients, we observed that cancer progression was associated with both increase in STAT3 expression and decrease in NFκB expression in peripheral blood cells." (PMID 33330068, 2020). "Cancer progression and inflammatory responses are associated with cytokines activitymediated by STAT-3." (PMID 32167126, 2020). "Aberrant activation of STAT3 is associated with many human malignancies, because STAT3 regulates numerous genes involved in tumorigenesis, progression, and drug resistance, and thus it has become an attractive cancer target." (PMID 32718354, 2020). "Cancer cells with elevated levels of activated STAT3 signaling are associated with a poor prognosis." (PMID 32549792, 2020). "Constitutive activation of the JAK1/STAT3 pathway is frequently observed in cancer cells while JAK2/STAT3 is closely associated with cytokine expression, cell apoptosis, and proliferation." (PMID 32895373, 2020). "In conclusion, STAT3 signaling is linked to cancer proliferation, survival, invasion, angiogenesis, metastasis, and inflammation, and has been shown to be an effective therapeutic target in RCC treatment." (PMID 30863721, 2019). "IL-6 is a prime stimulus for STAT3 activation and elevated serum levels of IL-6 have been associated with poor prognosis in various cancers." (PMID 31731457, 2019). "While STAT1 is often discussed as promoting antitumor activity—the flipside of STAT3-driven protumor signaling—STAT1 induction has also been implicated in cancer progression." (PMID 31842362, 2019). "Anti-IL-6/Stat3 and associated molecular pathways have shown great potential in anti-inflammation and cancer immunotherapy." (PMID 30922248, 2019). "STAT3 has received much attention for the important role it plays in signaling pathways linked to cancers." (PMID 31140150, 2019). "Treating cancers with hyperactivated or mutated STAT3 and STAT5 is currently achieved by targeting upstream kinases." (PMID 31817042, 2019). "Aberrations in the STAT3 pathway are intimately associated with the development of diverse cancer types." (PMID 31575017, 2019). "Upregulation of STAT3 has been demonstrated in cancer patients, in which the STAT3 activity was positively linked to poor prognosis." (PMID 31295906, 2019). "Those same authors also demonstrated that many other factors— including IL-6, RANTES, HGF, STAT3—implicated in the control of cancer cell growth and motility and considered targets for anticancer therapies, were downregulated after TARGIT8,44–46." (PMID 31133667, 2019). "Signal transducer and activator of transcription-3 (STAT3) has been widely reported to be associated with cancer progression, including ED." (PMID 31581950, 2019). "Taken together, our results link bypass of senescence with Stat3‐dependent stemness and metformin sensitivity and provide insights into the association between cancer and aging." (PMID 30614183, 2019). "The aberrant activity of STAT3 has been implicated in promoting the pro-oncogenic functions such as initiation, progression, metastasis, and immune evasion in different cancers." (PMID 31835318, 2019). "The STAT3 Tyr640Phe mutation has been identified in over >110 cancer cases in the COSMIC database and is most frequently observed in patients with T-LGLL." (PMID 31717342, 2019).
cancer (continued). "Persistently activated STAT3 is associated with excessive cell proliferation and survival in cancer cells, indicating that targeting STAT3 can decrease these properties of cancer cells." (PMID 31684051, 2019). "STAT3 induces the downstream genes encoding for cell cycle regulators, anti-apoptotic proteins, and angiogenic factors to participate in cancer development and progression." (PMID 31354479, 2019). "Capsaicin administration is linked to activation and/or inhibition of STAT3 phosphorylation in cancer cells." (PMID 30858408, 2019). "Aberrant activation of the signal transducer and activator of transcription 3 (STAT3) and the nuclear factor‐κB (NF‐κB) signalling pathways is associated with the development of cancer and inflammatory diseases." (PMID 30993883, 2019). "Because STAT3 activates multiple signaling pathways, aberrant activation can promote multiple changes associated with cancer, including altered cell cycle dynamics, EMT, angiogenesis, and interestingly, resistance to cell death." (PMID 30847405, 2019). "Constitutive STAT3 activation is associated with various human cancers and often suggestive of a poor prognosis, mostly related to inflammatory processes." (PMID 30975087, 2019). "Our data not only provide insight into the pathogenesis of HFD-associated PCa but also open new avenues for the study of other HFD-associated cancer growth in relation to STAT3 activity." (PMID 31474764, 2019). "Over the past decades, STAT3 has become one of the most investigated oncogenic transcription factors and is highly associated with cancer initiation, progression, metastasis, chemoresistance, and immune evasion." (PMID 31088482, 2019). "It has previously been shown that phosphorylated STAT3 (p-STAT3) is a substrate of PTPRD and that cancer-specific mutations in PTPRD abrogate the ability of the phosphatase to dephosphorylate STAT3." (PMID 31805999, 2019). "Activation of NF-kB and STAT3 resulting from an exposure to TR-rDNA can be one of the causes of the cancer cells resistance to the therapy." (PMID 31205871, 2019). "In cancer cells notably, STAT3 tends to be constitutively activated and had been associated with tumorigenesis and malignancy." (PMID 31140150, 2019). "Accumulating evidence, however, demonstrates dysregulation and constitutive activation of STAT3 that are associated with several human diseases including cancer." (PMID 31861597, 2019). "In the last years, miRNAs are emerging as important regulators of the JAK-STAT3 pathway in the pathogenesis of cancer, causing up- or downmodulation of STAT3 signaling, as well as in the development of chemoresistance in several types of cancer." (PMID 31781335, 2019). "One of the findings revealed that miR-196b-5p plays a central role in the maintenance of CSCs traits associated with chemoresistance to cancer therapeutic drugs via targeting STAT3 signaling pathway in CRC stem cells." (PMID 31530793, 2019). "NF-κB is highly associated with resistance to cancer therapies, while the overexpression and constitutive activation STAT3-NF-κB signaling pathway have been shown to confer chemoresistance in TNBC cells." (PMID 31088482, 2019). "STAT3 hyperactivation is an important hallmark in cancer initiation and progression, which can transcriptionally regulate the expression of a number of genes to enhance cell growth, migration, invasion, and angiogenesis." (PMID 30886152, 2019). "For many cancers, elevated levels of STAT3 signaling have been associated with a poor prognosis and the development of chemotherapy resistance." (PMID 32257917, 2019). "The signalling pathways linked to both STAT3 and NF-κB have been suggested to play important roles in the communication between inflammatory cells and cancer cells." (PMID 30962499, 2019).
cancer (continued). "Given the role of STAT3 signaling in regulating cell proliferation, vascular formation and immune response associated with cancer progression, it is important to explore novel targets that inhibit the ectopic activation of STAT3 signaling." (PMID 31921695, 2019). "These cytokines have been shown to activate NF-κB and signal transducers and activators of transcription 3 (STAT3), both of which have been implicated in cancer growth." (PMID 31510091, 2019). "IL-6 is a well-known activator of STAT3 and has been linked to the pathogenesis of several types of cancer, including colorectal cancer." (PMID 30679726, 2019). "We review here the role of STAT3/5 activation in solid cancers and summarize their association with survival in cancer patients." (PMID 31557897, 2019). "The migration and invasion of cancer cells into the bloodstream and surrounding tissues are critical steps in cancer metastasis, and the transcription of many target genes associated with these processes is regulated by STAT3." (PMID 31684051, 2019). "As a transcriptional factor, STAT3 plays a crucial role in promoting the progression of human cancers, including CRC, and is associated with adverse clinical outcome." (PMID 31534132, 2019). "In current researches, STAT3 is found to function as an oncogene and be highly activated in inflammatory‐associated cancer." (PMID 31222971, 2019). "Serine 727-phosphorylated STAT3 was found to physically associate with 14-3-3ζ in a proteomics screen for novel cancer-associated 14-3-3ζ-binding partners." (PMID 31130718, 2019). "Previous findings, including our own, have established that inhibition of constitutively activated STAT3 causes apoptosis in cancer cells." (PMID 30674340, 2019). "STAT-3 is able to induce expression of cysteine cathepsins, possibly in cooperation with another cancer-associated transcription factor, hypoxia-inducible factor-1-alpha, HIF-1α." (PMID 31555270, 2019). "While IL-6 family cytokines are important mediators of STAT3 activation, other cancer-associated receptors can also activate STAT3." (PMID 31684144, 2019). "Dysregulation of JAK2/STAT3 signaling pathway is associated with many cancer progression and metastasis." (PMID 31754348, 2019). "The STAT3 pathway regulates genes related to cell cycle and cell survival and is often linked to cancer progression." (PMID 31468250, 2019). "We herein showed that resveratrol and 5-FU combination treatments caused the anti-cancer activities by simultaneously inhibiting STAT3 and Akt signaling pathways." (PMID 30250641, 2018). "The NF-κB and JAK/STAT3 pathways mediate inflammatory response in cancer and are associated with poor prognosis in many malignancies." (PMID 29707119, 2018). "Persistent activation of STAT3 is associated with cancer growth and progression and is also involved in cell resistance to platinum and taxane treatment." (PMID 29849942, 2018). "Other than JAK activation, elevated levels and/or kinase activity of Src and other growth factor receptors have been indicated in several cancers, causing activation of STAT3." (PMID 30217007, 2018). "This lack is caused presumably because of the complexity of STAT3’s biology in normal as well as cancer cells and also because it lacks enzymatic activity, making it a challenging target." (PMID 29588647, 2018). "Constitutive activation of STAT3 has been found to be associated with initiation and progression of various cancers." (PMID 30217007, 2018). "Previous studies have demonstrated that PLOD2 expression is upregulated by both STAT3 and paracrine signals from cancer-associated fibroblasts (CAFs)." (PMID 30563531, 2018). "Transcription factor signal transducer and activator of transcription 3 (STAT3) has been shown to be closely associated with not only growth but also apoptosis in cancer." (PMID 30046347, 2018). "Persistent STAT3 activation has frequently been linked to more malignant cancer behaviors, including proliferation, invasion, and metastasis." (PMID 30154439, 2018).